BCL2 (BCL2 apoptosis regulator)
Diseases named in the same sentence as BCL2 in open-access papers (continued):
Sharing a sentence is not in itself a finding about the gene and the disease.
lymphoma (continued). "However, these correlation analyses have not yet been performed in larger panels of lymphoma cells, and a comparison across different tumor types in particular when including solid tumors may underestimate a potential role of BCL-2." (PMID 33308268, 2020). "However, more intensive regimens combining additional antineoplastic agents given in a continuous infusion such as DA-REPOCH have improved the overall survival of mediastinal primary lymphoma (PMBCL) and high grade lymphoma with BCL-2 and MYC genes rearrangement with or without BCL-6 rearrangement." (PMID 33121489, 2020). "Also, the mutation effects on TF binding at the promoter of two important FL genes (BCL6 and BCL2) were recovered: for example, regulatory activities of two TFs (FOXD2 and FOXD3) on BCL6 and BCL2 were confirmed previously by knockdown experiments in SUDHL4 lymphoma cell." (PMID 31001324, 2019). "However, lack of cIg LCs and lack of Bcl-2 overexpression do not rule out lymphoma." (PMID 26482649, 2015). "We therefore propose that autophagy activity in lymphoma samples may not be controlled by BCL-2." (PMID 25362242, 2014). "Lymphoma cells were small in size with mature chromatin, and positive for CD19, CD20, PAX5, and BCL-2, and negative for CD5, CD10, CD23, cyclin D1, and LEF1 (by IHC and/or flow)." (PMID 41357579, 2025). "Immunohistochemical staining demonstrated expression of CD10, CD20, BCL2, BCL6, and MUM1 by the lymphoma cells, while they were negative for CD5, CD15, CD23, CD30, and CD43." (PMID 39415926, 2024). "No MYC or BCL2 FISH discrepancies were found in any pair and, therefore, assessment for “double-hit” lymphoma would not have changed." (PMID 38903717, 2024). "One case was indeterminate due to the morphologic differential diagnosis of high-grade B-cell lymphoma-MYC/BCL2 versus follicular lymphoma with MYC and BCL2 rearrangements, which is not regarded as equivalent to “double-hit” lymphoma according to WHO5/ICC." (PMID 38903717, 2024). "Fluorescence in situ hybridization (FISH) analysis showed no rearrangements in BCL2, IRF4, or BCL6, and any deletion in the 1p36 region (TNFRSF14 gene), ruling out other lymphoma types." (PMID 39840177, 2024). "“Quadruple-hit” lymphomas, while not a defined entity in either the WHO or ICC classification schema, have been characterized by the concurrent presence of MYC, BCL2, BCL6, and CCND1 rearrangements, and are extremely rare with an apparent dismal prognosis." (PMID 38914869, 2024). "Among DLBCL cases, 55 were germinal center B-cell-like (GCB) lymphoma 47 were non-GCB; 23 cases were double expressors (C-MYC and BCL2-positive), and 13 cases were found to be triple expressors (C-MYC, BCL-2, and BCL-6-positive]." (PMID 39759724, 2024). "This category now consists of MYC and BCL2 rearranged cases exclusively, while the MYC/BCL6 double hit lymphomas now constitute genetic subtypes of DLBCL, not otherwise specified (NOS) or of HGBL, NOS." (PMID 37190213, 2023). "Regardless of HGBL-NOS or HGBL with MYC, BCL2 and/or BCL6 rearrangements (double/triple-hit lymphoma), the detection of MYC, BCL2 and BCL6 by FISH is necessary for a clear diagnosis." (PMID 37182167, 2023). "Another limitation was that the Swedish lymphoma register does not record molecular data, e.g. cell of origin, or MYC/BCL-2/BCL-6 translocations." (PMID 35999271, 2022). "The original lymphoma was of germinal center B‐cell phenotype, was MYC‐negative by immunohistochemistry (IHC), and had BCL2 rearrangement (BCL2‐R) without MYC‐R by interphase fluorescence in situ hybridization (FISH)." (PMID 36051039, 2022). "The lymphoma cells were positive for CD79a, PAX5, CD10 (diffuse), BCL‐6, MUM1, MYC, BCL‐2, CD3 (subset) and CD5 (subset), and negative for TdT and CD61, with a proliferation index of 80%." (PMID 36467806, 2022). "Immunohistochemistry stains of lymphoma cells were positive for CD20, CD79a, CD10, MUM1, BCL6, C-MYC, and negative for BCL2, cyclin D1, CD5, and CD3." (PMID 36120205, 2022).
lymphoma (continued). "HGBL-DH/TH lymphoma primarily have a GCB DLBCL phenotype, perhaps not surprising given that BCL2 translocations are almost exclusively found in GCB DLBCL." (PMID 35060000, 2022). "The lymphoma cells were positive for CD20, BCL‐6, MUM1, MYC and BCL2, and were negative for CD3, CD5 and CD10, diagnostic of DLBCL, non‐GCB type." (PMID 36467806, 2022). "In this new classification, the lymphoma subtype of this research is named diffuse large B-cell lymphoma/high-grade B-cell lymphoma with MYC and BCL2 rearrangements, and BCL6 is no longer included." (PMID 36497332, 2022). "Immunohistochemical analysis showed that the lymphoma expressed CD10, CD20, and BCL6 but was negative for CD34, BCL2, and TdT." (PMID 36171838, 2022). "To confirm the importance of Bcl-xL in ALCL, we made use of the Piccaluga Lymphoma dataset and observed significant upregulation of BCL2L1 (Bcl-xL) expression when compared to healthy donor T cells, whereas BCL2 and MCL1 were not significantly upregulated." (PMID 36045346, 2022). "Lymphoma cells expressing CD5 (CD5+) confer inferior outcome of diffuse large B-cell lymphoma (DLBCL), especially in non–MYC/BCL2 double expressor (non-DE) patients." (PMID 36276140, 2022). "Currently, aggressive B-cell lymphomas with a combined MYC- and BCL2 and/or BCL6 translocations (so-called double-hit or triple-hit, DH/TH lymphomas) are classified as a separate entity, irrespective of morphological features." (PMID 34099699, 2021). "Consistent with our previous findings, we see that silvestrol blocks the translation of the MYC and BCL2 mRNAs, without affecting the GAPDH housekeeping gene, across several lymphoma lines (SuDHL-4, SuDHL-6, SuDHL-10, Ly8)." (PMID 33562682, 2021). "Lymphoma cells were positive for CD20, CD10, Bcl‐2, Bcl‐6, cyclinD1, Ki67, c‐MYC and negative for CD30, CD5 and MUM‐1." (PMID 34698437, 2021). "BL is derived from a germinal center derived lymphoma, exhibiting BCL6, CD10, CD19, CD20, CD22, and CD79a expression and lacking CD5, BCL2, TdT, and, typically, CD23." (PMID 34283060, 2021). "Surprisingly, these studies in canine lymphoma cells reported no changes in the expression levels of XIAP, Mcl-1, Bcl-2, and Bcl-xL proteins following treatment with either flavopiridol alone or with the combination of flavopiridol and human TRAIL." (PMID 32260403, 2020). "The concomitant double expression of MYC and BCL2 is present in 20% to 30% of DLBCL; the group of DLBCL with these characteristics is termed double expressor lymphomas (DEL), but it is not a different biological entity." (PMID 31942539, 2019). "BCL2 expression is mostly absent in ALCL, ALK+ lymphomas but MCL1 expression can be detected in the majority of these lymphomas." (PMID 30131584, 2019). "The double-expresser lymphomas have a worse outcome than other DLBCLs but they are not as aggressive as the HGBL, with rearrangements of MYC and BCL-2 and/or BCL-6." (PMID 31288832, 2019). "Multiple hit lymphomas should be distinguished from “double expressor” DLBCLs in which MYC and BCL-2 genes are overexpressed at the protein level without the genetic rearrangements." (PMID 31115699, 2019). "Unlike BCL-2 and BCL-X, which are overexpressed in a subset of MCL, MCL-1 expression is typically low in this lymphoma." (PMID 30671383, 2018). "All CD19 negative lymphomas were positive for CD20, the majority was positive for PAX5, and two were positive for BCL2 and BCL6." (PMID 28484276, 2017). "When co-cultured with immune cells and endothelial cells, miR21-overexpressing B-lymphoma cells were resistant to chemotherapeutic agents, but sensitive to Bcl-2 inhibitor ABT-199, irrespective of Bcl-2 expression on lymphoma cells." (PMID 28637496, 2017).
lymphoma (continued). "An incisional biopsy from the left lacrimal gland revealed diffuse and intense CD20, CD5, and bcl-2 positivity with negative cyclin D1 and CD23 which supported lymphoma." (PMID 27738539, 2016). "These 40 cases are a pure group of MYC/BCL2 DHL, in other words no other DHL or triple hit lymphoma cases, and most patients received immunochemotherapy." (PMID 27203548, 2016). "Moreover, the immunohistochemical features, such as normally located bcl-2-positive cells only at the marginal zone, or preserved dense dendric cell network clearly demonstrated the non-tumoral nature of the lymphoid infiltration, and was enough to rule out malignant lymphoma." (PMID 25005726, 2014). "Almost all childhood “intermediate lymphoma” present with IG-MYC fusion, and BCL2 breaks are almost always absent." (PMID 22548066, 2012). "It inhibits anti-apoptotic proteins Bcl-2, Bcl-xL and Bcl-w, and unlike ABT 737, has shown single agent efficacy in numerous small cell lung carcinoma (SCLC) and leukemia/lymphoma cell lines." (PMID 21760983, 2011). "Whereas Sag exposure did not induce alterations in the expression of Bcl-2, TRAIL or TNFR1, interaction of Sags with the cognate Vβ chain of lymphoma T cells revert the low expression of Fas characteristic of these cells both in vitro and in vivo." (PMID 21203530, 2010). "The growth of lymphomas is typically supported by the expression of an anti-apoptotic protein; however, MMTV-RARαG303E lymphomas did not express BCL6, BCL2 or MCL1 (Results section), and preliminary data indicated that BCL-XL is weakly expressed." (PMID 16563162, 2006). "Immunohistochemistry can aid distinction: lymphoma cells in FL usually co-express BCL2, CD10, and BCL6, but BCL2 alone is not specific, as reactive aggregates may also show positivity." (PMID 41181806, 2025). "Of interest, these signatures identify not only aggressive lymphomas with this double hit status but also a significant number of lymphomas that do not harbor MYC and BCL2 rearrangements, although in some of them, retrospectively, cryptic rearrangements have been detected." (PMID 37190213, 2023). "Both in WHO-HAEM5 and the ICC, however, a fundamental change is that this entity comprises only cases with MYC and BCL2 rearrangements (DLBCL/HGBL-MYC/BCL2), with or without additional BCL6 breaks, so that aggressive lymphomas with dual rearrangements of MYC and BCL6 (without BCL2) are excluded." (PMID 37190213, 2023). "However, the IGH::BCL2‐positive cells may have the potential to develop into more than one lymphoma as the majority of transformed FLs do not progress directly from their preceding FL but originate via divergent evolution from their commonly related IGH::BCL2‐positive premalignant cell population." (PMID 37345526, 2023). "The third pathological investigation of the right paravascular iliac lesion indicated that the lymphoma had transformed into DLBCL (GCB subtype) that was negative for CD20 and positive for Bcl-6 (90%+), MUM1 (90%+), Ki-67 (80%+), Bcl-2 (90%+), c-myc (60%+), CD10 (+), and CD19(+)." (PMID 38143763, 2023). "The lymphoma was characterized by a cell-of-origin subtype of germinal center B-cell-like (GCB) based on Hans' classifier (CD10-negative, BCL6-positive, and MUM1-negative); EBER negativity, and the absence of BCL2, BCL6, and MYC rearrangements." (PMID 36975733, 2023). "Furthermore, in BCL2‐negative, MYC‐translocated lymphoma cell lines, the cytotoxic activity of IACS was potentiated by the Mcl‐1 inhibitor S63845." (PMID 34632715, 2022). "Therefore, the so-called “grey zone lymphomas” category has been removed and replaced with two new categories: “HGBL with MYC and BCL2 and/or BCL6 rearrangements”, or “HGBL-DH/TH”, and “HGBL not otherwise specified” (HGBL, NOS)." (PMID 34283060, 2021).
lymphoma (continued). "BCL2, BCL6 and MYC translocations are not mutually exclusive and may occur together in the same patient, forming the double-hit and even triple-hit lymphomas." (PMID 33996608, 2021). "Immunohistochemistry of intrathoracic biopsy revealed that the tumor cells were positive for CD20, CD30, c-Myc, BCL-2, Mum-1, and PD-L1 but negative for CD3, CD5, CD10, BCL-6, PD-1, and cyclin D1, conforming to the pathological diagnosis of diffuse large B-cell lymphoma (DLBCL))." (PMID 33564306, 2021). "Our three main findings are that a lack of a venetoclax response is primarily a consequence of pro-apoptotic protein dysfunction, the absence of BCL2 protein and the presence of MCL1, the initial finding being a novel feature of lymphomas with high-grade morphology." (PMID 33670870, 2021). "Lymphomas that co-express the MYC and BCL2 proteins, known as double-expressor lymphomas, are relatively frequent, and have a worse prognosis than other DLBCL-NOS, although their behavior is not as aggressive as that of the DH/TH lymphomas." (PMID 34207773, 2021). "In addition, although MYC, BCL2 and BCL6 rearrangements are important prognostic markers for patients with DLBCL, the sensitivity of lymphoma cell lines to DZNep-mediated apoptosis is independent of these rearrangements." (PMID 31419226, 2019). "Indeed, GSEA highlighted the proximity of 4-h-CTX-in vivo-challenged senescence-capable Eμ-myc lymphomas without Bcl2 protection and 5d-ADR-in vitro-senescent bcl2-engineered lymphomas based on similar ES of a large number of common gene sets in their expression profiles." (PMID 32686676, 2020). "However, prominent follicular colonization with numerous bcl-2+ lymphoma MALT cells may not be readily distinguished from the bcl-2+ neoplastic follicles of follicular lymphoma, and CD10 and bcl-6 may be difficult to interpret as either residual germinal centers or as lymphoma cells." (PMID 37958219, 2023).
leukemia (594 papers, 2002 to 2026). A malignant (clonal) hematologic disorder, involving hematopoietic stem cells and characterized by the presence of primitive or atypical myeloid or lymphoid cells in the bone marrow and the blood. "ETP‐ALL is a stem cell‐like leukemia characterized by poor differentiation; thus, BCL2 dependence represents a universal and hallmark feature of this disease." (PMID 41394964, 2025). "This inactivation caused growth inhibition of the leukemia cells while also inhibiting the activation of the survival genes Bcl2 and survivin by c-Myc and LEF-1." (PMID 40805157, 2025). "Aberrant expression of BCL2 is frequently observed in high-risk leukemias, including pediatric subtypes, in which it contributes to chemoresistance and poor prognosis." (PMID 40965810, 2025). "This revealed binding of MYB::PLEKHO1 to the transcription start sites of BPDCN-associated genes such as Il3ra (CD123), Bcl2, and Myc, which were strongly expressed in leukemia cells." (PMID 39499902, 2024). "Another study reported an increased susceptibility to leukemia having Bcl-2 -938C>A and Bax -248G>A SNPs that influenced their response to treatment and overall survival." (PMID 39205918, 2024). "The data specified that there was an association between the mutant allele of Bcl-2 -938C>AC>A and the Bax -248G>A gene and a significantly increased risk of developing leukemia, compared to the wild-type allele." (PMID 39205918, 2024). "For example, we find that increased dependency on BCL2 is associated with leukemia, myeloma, and MEF2B mutations." (PMID 35382456, 2022). "Collectively, these results indicate that expression of ROR1 can enhance the viability of the venetoclax-treated leukemia cells, including leukemia cells that expressed mutant forms of BCL2 associated with venetoclax resistance." (PMID 35418613, 2022). "Bcl-2-induced ROS generation in leukemia cells is associated with increases in cellular oxygen utilization, cytochrome c oxidase/complex-IV activity, and mitochondrial respiration." (PMID 36139768, 2022). "Blockage with HSP90-specific inhibitor geldanamycin (GA) also diminishes the association of HSP90 with APAF-1 or BCL-2 in leukemia cells, leading to apoptosis." (PMID 36139353, 2022). "Bcl-2 is upregulated in the highly aggressive early T precursor (ETP) leukemia, which underlies its sensitivity to venetoclax." (PMID 33777761, 2021). "As a signaling pathway that regulates cell apoptosis and survival, the Bcl-2/Cleaved caspase-3 apoptotic pathway has been implicated in many cancers including leukemia." (PMID 34568314, 2021). "In vivo leukemogenesis assay was performed on Sox4+/+ or Sox4–/– embryos as in A (C) Effects of Bcl2- or Sox4-deficiency on the maintenance of leukemia initiating cells." (PMID 34310280, 2021). "Enforced expression of B cell lymphoma oncogenes such as MYC, NMYC or BCL2, in the B cell compartment or loss of tumor suppressors can also skew MuLV driven malignancies toward B cell lymphoma and leukemias." (PMID 34484175, 2021). "Specifically, one group has recently demonstrated that the IDH1 R132H mutation sensitizes leukemia cells to the cytotoxic effect of the selective Bcl-2 inhibitor ABT199." (PMID 34209035, 2021). "We aimed to elucidate the prognostic role of CD200/BCL2 co-expression and its association with specific leukemia subsets." (PMID 33596632, 2021). "The BCL2 protein is expressed in many non-Hodgkin lymphomas (NHLs) as well as associated leukemias, e.g., chronic lymphocytic leukemia (CLL)." (PMID 33670870, 2021). "This is in agreement with previous results, in which crocin is shown to affect the Bax/Bcl2 ratio to cause apoptosis in Leukemia, lung cancer, AGS gastric cancer and prostate cancer cells." (PMID 32604971, 2020). "Apoptosis has been reported as a hallmark for various cancer types, including leukaemia, and overexpression of anti-apoptotic BCL2 protein plays an important role in the regulation of apoptosis." (PMID 32183192, 2020).